TXNRD1 (thioredoxin reductase 1)
Diseases named in the same sentence as TXNRD1 in open-access papers (continued):
Sharing a sentence is not in itself a finding about the gene and the disease.
tumor (continued). "The TXNRD1, GPX1, and GPX2 genes may exert dual effects in tumor mutagenesis and development, while the TXNRD1, GPX1, GPX2, and GPX3 genes were found to be related to drug sensitivity or the formation of drug resistance." (PMID 33706760, 2021). "Moreover, miR-1305 was observed to exert a tumor-suppressive effect in ESCC cells by directly targeting and repressing TXNRD1." (PMID 33292234, 2020). "Since TrxR is also involved in tumor growth and DNA replication, it is not surprising that TXNRD1 overexpression has been evidenced in many aggressive tumors." (PMID 30791480, 2019). "Our results implicate that PCK1 acts as a tumor suppressor in HCC and combination therapy of sorafenib and TXNRD1 inhibitors may be a novel strategy for HCC treatment." (PMID 30619751, 2018). "Mice lacking the selenoprotein thioredoxin reductase 1 (TXNRD1) in liver manifested a dramatically higher incidence of tumor development than control mice expressing TXNRD1 when both mouse lines were treated with a liver carcinogen, DEN." (PMID 26569310, 2015). "However, we only detected positivity for Arg1, suggesting macrophages in these models are immunosuppressive regardless of tumor GSR/TXNRD1 status." (PMID 40334547, 2025). "Its downregulation in HCC has been demonstrated to contribute to tumor invasion and progression by promoting epithelial–mesenchymal transition (EMT) and by increasing polyunsaturated lipids and subsequent ROS production as well as lipid peroxidation via activating NRF2/TXNRD1 pathway." (PMID 35898502, 2022). "The differential effects on tumor initiation and early progression following GSR and TXNRD1 ablation in KrasG12D/+ tumors suggests non-overlapping functions; however, in both models, tumors were still able to form." (PMID 40334547, 2025). "We found that tumor initiation was promoted by expression of GSR, but not TXNRD1, regardless of Nrf2 status." (PMID 40334547, 2025).
infection (10 papers, 2012 to 2025). The state of being infected such as from the introduction of a foreign agent such as serum, vaccine, antigenic substance or organism. "GPX4 and TXNRD1, selenoprotein antioxidant genes responsible for maintaining cellular homeostasis and protection against oxidative stress and hydroperoxides, demonstrated limited modulation after infection." (PMID 41157575, 2025).
cardiovascular diseases (4 papers, 2018 to 2023). "Thioredoxin system is composed of the anti‐oxidant thioredoxin‐1 (TXN1), thioredoxin reductase (TXNRD1), thioredoxin peroxidase‐1 (PRDX1), and the pro‐oxidant thioredoxin‐interacting protein (TXINP), which functions as a crucial defense mechanism against oxidative damage in cardiovascular diseases." (PMID 32618439, 2020).
movement disorder (2 papers, 2008 to 2022). Neurological conditions resulting in abnormal voluntary or involuntary movement, which may impact the speed, fluency, quality and ease of movement. "Mice with targeted deletion of thioredoxin reductase 1 (Txnrd1) in the nervous system displayed growth retardation and movement disorders, suggesting a specific role of Txnrd1 in brain development and function." (PMID 35565817, 2022). "NS-specific Txnrd1 knockout mice were born at the expected frequencies, but displayed growth retardation and striking a movement disorder, suggestive of cerebellar dysfunction." (PMID 18350150, 2008).
neurodegenerative disease (2 papers, 2008 to 2023). A disorder of the central nervous system characterized by gradual and progressive loss of neural tissue and neurologic function. "Since oxidative stress has been linked with neurodegenerative disease, we studied the roles of thioredoxin reductases in brain using mice with nervous system (NS)-specific deletion of cytosolic (Txnrd1) and mitochondrial (Txnrd2) thioredoxin reductase." (PMID 18350150, 2008). "The results indicate that TXNRD1 from the membrane and cytosol could be the reductase from the glutathione system that switches the TMX on-off at the different locations, including the ER, connecting its function with protein unfolding with many pathologies, including neurodegenerative diseases." (PMID 38086796, 2023).
TXNRD1 also shares sentences with these, for which no sentence is quoted: head and neck cancer (4 papers); thyroid cancer (4); Cerebral ischemia (3); ischemia (3); multiple myeloma (3); osteosarcoma (3); squamous cell carcinoma (3); adenocarcinoma (2); autism (2); breast (2); cardiomyopathy (2); chronic lymphocytic leukemia (2); COVID-19 (2); cyst (2); gastric tumors (2); Huntington disease (2); idiopathic pulmonary arterial hypertension (2); leukemia (2); neuroblastoma (2); oligodendroglial tumours (2); oral squamous cell carcinoma (2); abdominal aortic aneurysm (1); acute leukemia (1); acute myeloid leukemia (1); acute respiratory distress syndrome (1); age-related macular degeneration (1); allergic disease (1); aortic valve stenosis (1); autosomal recessive spastic paraplegia (1); B-cell lymphomas (1).
A further 46 diseases each share a sentence with TXNRD1 in 1 paper.